TLR3 (toll like receptor 3)
Diseases named in the same sentence as TLR3 in open-access papers (continued):
Sharing a sentence is not in itself a finding about the gene and the disease.
infection (continued). "The up-regulatory effect on MyD88 and TRIF may be the result of direct viral interaction or the up-regulation effect on cell-membrane- (TLR2 and TLR4) and endosomal-associated (TLR3, TLR8, and TLR9) TLRs induced by single-PDCoV infection." (PMID 36376395, 2022). "However, our findings are in contrary to another study that found an upregulation of TLR3 24 h after a pI:C infection due to a prior 2 h‐exposure to a aqueous‐trapped solution of diesel exhaust." (PMID 34542243, 2021). "This increased expression suggests that TLR7 and TLR8 may be more relevant than TLR3 in modulating infections with hMPV." (PMID 33809875, 2021). "TLR3 is a receptor for dsRNA produced from infection by dsRNA viruses." (PMID 34835955, 2021). "However, these authors also reported that TLR3 inhibition in astrocytes caused a significant decrease of IFN-β, RANTES, and IP-10 secretion after infection with a Puerto Rican strain of ZIKV." (PMID 33658344, 2021). "In order to combat the infection, TLR3 binds with the hemagglutinin spikes of the influenza virus." (PMID 34970593, 2021). "Interestingly, MDA5 and TLR3 exert different IFN-I response kinetics following EMCV-D infection in C57BL/6 mice, with IFN-I responses detected in MDA5-/- at 15 hours post-infection and at a later time in TLR3-/- mice." (PMID 34804036, 2021). "A paper published by the Vidal lab reported that RIG-I, the PRR directly upstream from MAVS and responsible for its activation, as well as TLR3, responded to infection by another RNA virus, influenza A virus, through type 1 interferon signaling, resulting in a positive feedback loop." (PMID 34310619, 2021). "Some experiments that could be useful to address the role of TLR3 during hMPV infections may involve the use of mice knockout (KO) for or overexpressing TLR3 or the direct use of antagonists against TLR3 on in vivo assays, such as blocking antibodies." (PMID 33809875, 2021). "Agonist stimulation assay showed that MAVS and STING signaling possessed significant anti-PRRSV activities, whereas siRNA knockdown assay showed that TRIF, MAVS and STING are all involved in anti-PRRSV activity, with TLR3-TRIF displaying discrepancy in anti-PRRSV infection." (PMID 34696285, 2021). "Overall, exposure to PRRSV1 did not induce maturation of cDC1, cDC2, or CD14+ DCs, but modified TLR3 and TLR7-associated responses (except for cDC1), which may affect the development of adaptive immunity during PRRSV1 infection." (PMID 34177915, 2021). "Similar to MDA5+/- mice, at day 7 following CB4 infection in comparison to wt mice, TLR3+/- mice have significantly increased regulatory Foxp3+ T cells in the pancreatic lymph nodes (PLNs) and in the spleen, while statistical significance was not achieved, there was a propensity for increased Tregs." (PMID 34804036, 2021). "Depending on their levels of expression and the timing and location of signaling, MDA5 and TLR3 can also protect from the onset of autoimmune diabetes following infection with diabetogenic viruses like coxsackieviruses and the pancreatropic RNA virus encephalomyocarditis virus strain D (EMCV-D)." (PMID 34804036, 2021). "However, DHF patients with high IgG1 levels were more likely to be TLR3-rs3775291-C/T, and who presented a secondary infection had a lower probability of being TLR3-rs3775291-T/T." (PMID 33138336, 2020). "In addition to the HBV-induced repression of RIG-I, this is a consequence of impaired MDA5 and TLR3 pathways during infection." (PMID 33613561, 2020). "We next explored whether activation of TLR3 leads to augmentation of the bacterial product induced inflammation in VECs, AECs and myocytes in a model of ascending infection/inflammation." (PMID 32983111, 2020). "Some evidence from Friend virus infection in mice indicates TLR3 may make a minor contribution to the CD8 T cell response to infection." (PMID 33202596, 2020).
infection (continued). "However, DHF patients with high IgG1 levels were more likely to be TLR3-rs6552950-A/G, and who presented a secondary infection had a lower probability of being TLR3-rs6552950-A/G." (PMID 33138336, 2020). "Only Mx1 showed a significant increase in WT and TLR3 KO DF-1 cells after AIV infection." (PMID 32425931, 2020). "Tlr3–/– KO mice exhibit higher survival rates with lower viral titers, lower production of mediators of inflammation, and fewer pathological alterations in their lungs after IV infection than their wild-type counterparts." (PMID 32689931, 2020). "Taken together, our data demonstrate the capacity for signalling via TLR3 to activate the key transcription factors known to regulate pro-labour and pro-inflammatory mediators in a situation of ascending infection, systemic inflammation and haematogenous spread of infection induced PTL." (PMID 32983111, 2020). "In addition to antagonizing apoptosis mediated by poly(I·C), a reported TLR3 agonist and dsRNA homolog, we report that Npro expressed stably in cell culture and during infection can also antagonize SeV-mediated apoptosis." (PMID 33328306, 2020). "The clinical relevance of TLR signaling in the context of these two hepatotropic viruses has been highlighted by the identification of single nucleotide polymorphisms (SNPs) present in the TLR3 and TLR9 genes, as they are associated with the clinical course of infection." (PMID 33613561, 2020). "There was no significant impact on transcription of any of the claudin genes tested when IFN-β was added to OE-TLR3(-) cells 1hr before infection, except for the 36hr timepoint when claudin-3 transcription was significantly higher in the IFN-β pre-treated TLR3-deficient OE cells." (PMID 30625140, 2019). "We speculate that the upregulation of TLR3 may play a similar role in response to infection with the attenuated DHAV-3 strain." (PMID 31514454, 2019). "Myd88-deficient mice infected with CHIKV, like TLR3−/− mice, did not succumb to infection but developed significant viral dissemination." (PMID 30909385, 2019). "The TLR3 signal also causes an upregulation of TLR2, which participates in the expression of IL1β, IL6, CCL2, and CCL5 genes by primary C57BL/6 astrocytes following a TMEV-BeAn infection." (PMID 30669615, 2019). "In our study, the data of western blot proved that infection of influenza virus could increase the expression of the innate immune system-related factors TLR3, TAK1, TBK1, IRF3, and IFN-β in Raw264.7 cells." (PMID 31975996, 2019). "During the course of conducting the current study, a study reported that TLR3 signaling in macrophages was required for invariant natural killer T (iNKT) cell activation during EV-A71 infection, and that this iNKT population played a key role in defending against EV-A71 infection in vivo." (PMID 30563052, 2018). "Thus, we assessed the involvement of Trif and TAPE in coupling TLR3 signaling to type I IFN induction during EV-A71 infection." (PMID 30563052, 2018). "In the same experiments, the authors demonstrated that mice lacking MDA5 succumbed to the infection more rapidly than TLR3-deficient mice and produced less IFN-β at 24 h post-infection." (PMID 30369921, 2018). "Interestingly, at 4 hours post infection, A20 expression was higher in LgyLRV1+ infected macrophages, compared to LgyLRV1- or Poly (I:C) stimulation, suggesting an additive role for TLR3 stimulation." (PMID 29487860, 2018). "TLR3 is known for detecting viral dsRNA during an RNA virus or some DNA virus (like HSV) infection." (PMID 30563052, 2018). "Although the mechanism by which TLR3 is modulating the response in experimental infection has been clarified, we can suggest that the fungus uses this receptor as an escape mechanism and that one of the pathways could be through the regulation of CD8 T cells." (PMID 30687643, 2018).
infection (continued). "However, our in vivo data showed that IFN-β likely modulates Chlamydia growth during early infection as IFN-β synthesis induced via TLR3 was simply elevated between day 6 and 8 of genital tract infections in wild-type mice." (PMID 29624589, 2018). "In addition to EV-A71 infection, EV-A71-infected, RNA-induced TLR3 signaling to IFN-β activation was also abolished by the silencing of Trif or TAPE." (PMID 30563052, 2018). "Here, we show for the first time that TLR3 modulate the infection against Paracoccidioides brasiliensis by dampening pro-inflammatory response, NO production, IFN+CD8+T, and IL-17+CD8+T cell activation and cytotoxic function, associated with granzyme B and perforin down regulation." (PMID 30687643, 2018). "Interestingly, TLR3 has been implicated in RNA virus recognition, while a human DNA tumor virus up-regulating TLR3 during primary infection is also reported." (PMID 29304016, 2018). "It has already been described in the literature the importance of these cells in the control of this infection and as TLR3 interferes in this response, as we saw in our results, it could be this way that the fungus uses to survive in the tissue." (PMID 30687643, 2018). "Groups of five wild-type and five TLR3-/- mice were infected intravaginally with 105 IFU C. muridarum before being sacrificed at either day 7 or day 21 of infection, and their lower genital tracts processed for flow cytometry as described in Materials and Methods." (PMID 29624589, 2018). "Late in infection, we found that dsRNA colocalized with TLR3 and RIPK1 in vesicular structures." (PMID 29449668, 2018). "We previously showed that TLR3-/- mice bred in the 129S1 background exhibited significantly higher levels of chlamydial shedding from the genital tract when compared to wild-type mice within the first four weeks of infection." (PMID 29624589, 2018). "The TLR3 protein level was decreased after EV-A71 infection in a dosage-dependent manner." (PMID 30563052, 2018). "In combination with previous research, our current work suggests that EV-A71 proteases may help to subvert the TLR3-Trif pathway to facilitate EV-A71 infection and replication in host cells." (PMID 30563052, 2018). "Viral double-stranded RNA derived from EV-A71 infection was a key ligand for TLR3 detection." (PMID 30563052, 2018). "It is likely that the TLR3 induced augmentation of TLR2 activity is absent early times during infection during TLR3 deficiency, and is what contributes to an aberrant immune response to C. muridarum in the TLR3 deficient mice." (PMID 29624589, 2018). "We hypothesized that expressions of TLR3 and type I IFNs and macrophage recruitment will be increased following in ovo or post-hatch delivery of dsRNA and infection with LPAIV, when these changes are observed in lungs, resulting in decreased LPAIV replication." (PMID 29530062, 2018). "Furthermore, it was found that TLR4 and nucleolin levels increased early after infection and decreased subsequently, whereas TLR3 and TLR7 expression increased throughout RSV infection." (PMID 29427996, 2018). "Results showed that the percentages of IL-4-, IL-5-, and IL-17-producing cells in TLR3+ NK cells population significantly increased after infection (IL-4: 14.73 ± 1.968% versus 8.787.97581%; IL-5: 0.03333 ± 0.03333% versus 0.9833 ± 0.1922%; IL-17: 24.50 ± 2.466% versus 51.76 ± 2.258%, P < 0.05)." (PMID 30246036, 2018). "During the later stage of infection (60 hpi, 72 hpi), TLR3 and TLR7 expression gradually increased." (PMID 29700351, 2018). "Additionally, TLR3−/− mice were infected with S. japonicum to further evaluate the role of TLR3 on NK cells during infection." (PMID 30246036, 2018). "TLR3 deficiency in mice led to increased synthesis of TNF-α, IFN-γ, and IL-10; however, IFN-β, IL-1β, and IL-6 were secreted into the genital tracts of wild-type mice at significantly higher levels than in TLR3-/- mice during early infection." (PMID 29624589, 2018).
infection (continued). "In contrast, no role for TLR3 signaling could be demonstrated during experiments in which TLR3 was silenced by siRNA before infection with a wild-type isolate of HCMV." (PMID 28046022, 2017). "In contrast, TLR3 KO mice succumbed to infection with 108 viruses in less than 8 days." (PMID 28973047, 2017). "Alternatively, viral RNA intermediates produced upon infection may stimulate the RIG-I or TLR3 pathway in DCs35." (PMID 28150813, 2017). "However, pancreases from TLR3 KO mice exhibited more severe edema and tissue damage, while pancreases from WT mice had some intact acinar structures 12 days post-infection." (PMID 28973047, 2017). "Interestingly, in the MAA condition, TLR3 was only significantly up regulated at 240 minutes post infection perhaps suggesting a delayed TLR response." (PMID 27653506, 2016). "However, when MSCs were treated with the TLR3/dsRNA complex inhibitor during RSV-infection they had reduced IFN-β and IDO, suggesting a role for TLR3 in the observed response to RSV in MSCs." (PMID 27695127, 2016). "It was further confirmed that TLR3 pathway was involved in P815 cell response to IAV-infection." (PMID 28127293, 2016). "In the coinfection setting, IAV primes DCs to secrete type I IFNs and other soluble factors, which trigger changes in the surrounding DCs, including enhanced expression of TLR3, which prime the cells to react with increased IL-12p70 production in the secondary infection with pneumococci." (PMID 26956584, 2016). "Previous studies have demonstrated that the amount of RSV strain A used to infect human epithelial kidney cells directly correlated with the level of CXCL8/IL-8 and RANTES produced in response to infection, and chemokine production in response to infection was dependent on TLR3 expression." (PMID 26732674, 2016). "In addition, treatment of IAV-infected P815 cells with TLR3/dsRNA complex inhibitor dramatically decreased viral titers 24 and 36 h after infection." (PMID 28127293, 2016). "Our findings in cervical tissues demonstrated enhanced TLR3 expression by poly (I:C) only on day 3 after infection, which was associated with no change in HIV-1 RNA expression in poly (I:C) treated compared with untreated control tissues." (PMID 26121689, 2015). "TLR3 recognizes viral double-stranded RNA (dsRNA) during infection." (PMID 26313906, 2015). "TLR3 mainly recognizes dsRNA molecules that are formed during viral genome replication or transcription and localizes exclusively in intracellular vesicles such as endosomes and the endoplasmic reticulum, in which viruses undergo un-coating during infection." (PMID 26634454, 2015). "TLR3 transcription appears to decrease later on during the infection, which is indicative that TLR3 likely plays a lesser role in the pathogenesis of Chlamydia infected OE cells at late times during the infection." (PMID 25798928, 2015). "Compared to the mock-infected ducks at 24 hpi, the lungs of SS-10-infected ducks during the first 3 days of infection showed upregulation that peaked in the mRNA expression level of TLR3 (95.36-fold), TLR7 (146.35-fold), RIG-I (26.29-fold), MDA5 (4.22-fold), and LGP2 (4.77-fold)." (PMID 26635752, 2015). "At this dose of virus, half of the WT mice were paralyzed and died within 8 days post-infection, while none of the TLR3-deficient mice survived beyond 5 days post-infection." (PMID 25615690, 2015). "Moreover, transcriptional start sites (TSSs) and isoforms, as well as differential promoter usage, revealed a complex pattern of transcriptional and post-transcriptional gene regulation upon infection with TLR3 and TLR4." (PMID 26159724, 2015). "In conclusion, our studies suggest that higher basal levels of TLR3/7 and augmented innate antiviral immune responses upon infection may afford resistance to PPRV infection in Kanni and Salem breeds of goats compared to Barbari and Tellicherry breeds." (PMID 25369126, 2014).
infection (continued). "In our model, the TLR3 gene appears significantly induced from the first day post-viral injection, and this induction is even more significant (p<0.0002) at days 2 and 5 post-infection." (PMID 25338079, 2014). "Infection with Theiler`s murine encephalomyelitis virus requires sensing of both TLR3 and MDA5." (PMID 25539593, 2014). "Based on the significant difference in TLR3 expression in eMDM stimulated with EIAVFDDV13 and EIAVUK3, we hypothesize that TLR3 pathway activation plays an important role in the induction of infection resistance by EIAVFDDV13 infection in macrophages in vitro." (PMID 25106750, 2014). "Furthermore, we observed that some cellular factors involved in the activation of innate immunity by EIAVFDDV13, which occurred primarily through TLR3 activation, were important contributors to the development of infection resistance." (PMID 25106750, 2014). "Specifically, a model was proposed that RIG-I may be responsible for the immediate early response to infection and that the function of TLR3 may be in sustaining this response." (PMID 25127040, 2014). "As expected, all TLR3−/− (H-2b) mice succumbed to JE after infection with two different doses of JEV (1.4×107 and 2.8×107 pfu), while wild-type (H-2b) mice showed similar 50% and 70% mortality to wild-type mice of mouse strain (H-2d) used for TLR3−/− mice, respectively." (PMID 25188232, 2014). "Moreover, it was demonstrated that RSV promotes a predominant Th1-type response when TLR3 is activated during the infection." (PMID 24860569, 2014). "Taken together, analysis of the characteristic cellular responses to infection revealed that although high levels of TLR3 expression increased IRF3 phosphorylation in response to WNV infection at late times, the TLR3 status did not affect infectivity, viral genome replication or WNV-induced CPE." (PMID 25127040, 2014). "This contrasting regulation of JE by TLR3 and TLR4 molecules was more apparent (p = 0.0314 for TLR3 and p = 0.0342 for TLR4), when we evaluated the susceptibility of TLR3−/− and TLR4−/− mice to neuroinflammatory diseases after infection with a higher dose of JEV (2.8×107 pfu)." (PMID 25188232, 2014). "Strikingly conflicting role of TLR3 signal pathway was derived from an infection model with WNV." (PMID 25188232, 2014). "Compared to wild-type mice, resistance to primary infection and to re-challenge was similar in TLR9-deficient or TLR6-deficient mice; it was greatly increased in TLR2-deficient mice but impaired in TLR3- or TLR4-deficient mice." (PMID 23853597, 2013). "TLR3 recognizes dsRNA formed during viral genome replication or transcription, and is localized exclusively in intracellular vesicles such as the endosome and endoplasmic reticulum (ER) where viruses undergo uncoating during infection." (PMID 24016341, 2013). "Furthermore, in both the in vitro and in vivo experiments, the TLR3 levels were significantly increased after RSV infection compared with hMPV infection." (PMID 24039959, 2013). "To interrogate which PRR is essential for mycobacteria-induced MCP-2/CCL8 production in macrophages, we compared mRNA levels of mcp-2/ccl8 among macrophages from wild-type, TLR2−/−, TLR3−/− or TLR4−/− mice after infection with either BCG or H37Rv at an MOI 5 for 24 h." (PMID 23418602, 2013). "Indeed, TLR3−/− mice, in these infections, have an increased survival rate when compared to their wild type." (PMID 22919688, 2012). "Therefore, the mechanism(s) for the suppression vs. partial reduction of infection upon TLR3/4 and TLR7/9 engagement, respectively, remained unclear." (PMID 23028330, 2012). "The relative contribution of the RLRs, PKR and Tlr3 might therefore vary depending on the course of infection or the time point of the analysis." (PMID 22570612, 2012).